MEST (mesoderm specific transcript)
Diseases named in the same sentence as MEST in open-access papers (continued):
Sharing a sentence is not in itself a finding about the gene and the disease.
metabolic disorders (1 paper, 2025). "Studies have consistently demonstrated that PFAS compounds can induce changes in DNA methylation at imprinted loci such as IGF2 and MEST, thereby influencing fetal growth trajectories and increasing susceptibility to metabolic disorders." (PMID 40566344, 2025).
MEST also shares sentences with these, for which no sentence is quoted: Beckwith-Wiedemann syndrome (1 paper); Biotin deficiency (1); cervical cancer (1); choriocarcinoma (1); diabetes (1); dyslipidemia (1); endometriosis (1); esophageal squamous cell carcinoma (1); fetal growth restriction (1); invasive breast carcinoma (1); placental disorders (1); rhabdomyosarcoma (1); thyroid cancer (1); transient neonatal diabetes mellitus (1); type-2-diabetes (1); Zinc deficiency (1).